TMED1 (transmembrane p24 trafficking protein 1)
Description:
Potential role in vesicular protein trafficking, mainly in the early secretory pathway. May act as a cargo receptor at the lumenal side for incorporation of secretory cargo molecules into transport vesicles and may be involved in vesicle coat formation at the cytoplasmic side. Plays a positive role in IL-33-mediated IL-8 and IL-6 production by interacting with interleukin-33 receptor IL1RL1. Also plays a role in the modulation of innate immune signaling through the cGAS-STING pathway by interacting with RNF26.
Synonyms: Tp24; p24gamma1; IL1RL1L; IL1RL1LG; ST2L; MGC1270; p24g1
Tractability: Antibody: UniProt places it where antibodies can reach, with high confidence; UniProt predicts a signal peptide or a membrane-spanning region; its Gene Ontology location is reachable by antibodies, with medium confidence. PROTAC: ubiquitination databases record sites on it; its protein half-life has been measured.
Gene: Protein-coding gene on chromosome 19 (10,832,067 to 10,836,318, reverse strand). Ensembl gene ENSG00000099203.
Subcellular location: Cell membrane; Endoplasmic reticulum membrane; Golgi apparatus, cis-Golgi network membrane; Endoplasmic reticulum-Golgi intermediate compartment membrane
Gene Ontology:
Molecular function: protein binding; signaling receptor binding
Biological process: cell-cell signaling; endoplasmic reticulum to Golgi vesicle-mediated transport; Golgi organization; signal transduction
Cellular component: endoplasmic reticulum; endoplasmic reticulum membrane; endoplasmic reticulum-Golgi intermediate compartment; endoplasmic reticulum-Golgi intermediate compartment membrane; Golgi apparatus; plasma membrane
Genetic constraint (gnomAD): Loss-of-function variants: 20 observed, 20.24 expected, observed/expected ratio (o/e) 0.99, 90% interval 0.69 to 1.43. The upper end of that interval is the gene's LOEUF score, 1.43, which puts it in group 5 of 6, group 1 being the genes least tolerant of losing a copy. Missense variants: 316 observed, 304.65 expected, observed/expected ratio (o/e) 1.04, 90% interval 0.94 to 1.14. Synonymous variants: 149 observed, 135.71 expected, observed/expected ratio (o/e) 1.1, 90% interval 0.96 to 1.26.
Homologues: Orthologues: chimpanzee TMED1 (100% identical), macaque TMED1 (99% identical), pig TMED1 (98% identical), mouse Tmed1 (95% identical), rat Tmed1 (95% identical), rabbit TMED1 (94% identical), guinea pig TMED1 (93% identical), dog TMED1 (90% identical), tropical clawed frog tmed1 (65% identical), zebrafish tmed1b (59% identical), zebrafish tmed1a (50% identical), Drosophila melanogaster p24-1 (26% identical), and 1 more. Paralogues in human: TMED5 (52% identical), TMED7 (33% identical), TMED3 (31% identical), TMED9 (22% identical), TMED2 (21% identical), TMED4 (21% identical), TMED6 (21% identical), TMED10 (17% identical).
Diseases named in the same sentence as TMED1 in open-access papers:
TMED1 is named in the same sentence as 7 diseases in open-access papers, as found by Europe PMC text mining. Sharing a sentence is not in itself a finding about the gene and the disease. The quoted sentences say what the papers report.
asthma (1 paper, 2021). "Predictive interaction analysis revealed strong physical interactions between IL1RL1 and TMED1 which is unsurprising as both are related to IL33 signaling which has been extensively researched in the context of asthma." (PMID 35386986, 2021).
colorectal cancer (1 paper, 2024). A primary or metastatic malignant neoplasm that affects the colon or rectum. "The results indicated that TMED1, functioning as an oncogene, is upregulated in colorectal cancer and exhibits a significant association with an unfavorable prognosis." (PMID 38392302, 2024). "In brief, TMED1 can serve as a promising therapeutic target and an unfavorable prognostic biomarker for colorectal cancer." (PMID 38392302, 2024). "Thirdly, further experiments in vitro and in vivo should be performed to prove the impact of TMED1 on the growth of colorectal cancer and clarify the specific mechanism." (PMID 38392302, 2024). "Consequently, TMED1 emerged as a promising candidate biomarker for assessing the progression and prognosis of colorectal cancer." (PMID 38392302, 2024). "In this study, the expression and prognostic significance of the transmembrane p24 trafficking protein 1 (TMED1) in colorectal cancer were investigated by utilizing patient survival data and multi-omics datasets, including immunohistochemical staining, transcriptomics, and proteomics." (PMID 38392302, 2024). "However, the expression level and biological role of TMED1 in colorectal cancer (CRC) have yet to be fully elucidated." (PMID 38392302, 2024). "Additionally, a positive correlation was identified between TMED1 and other members of the TMED family (TMED2, TMED4, TMED9, and TMED10) in colorectal cancer." (PMID 38392302, 2024).
cancer (1 paper, 2024). A tumor composed of atypical neoplastic, often pleomorphic cells that invade other tissues. "Our findings showed that TMED1 expression was positively correlated with Tregs, cancer-associated fibroblasts, and endothelial cells." (PMID 38392302, 2024). "Furthermore, TMED1 expression was positively associated with the infiltration levels of regulatory T cells (Tregs), cancer-associated fibroblasts (CAFs), and endothelial cells and negatively correlated with the infiltration levels of CD4+ T cells, CD8+ T cells, and B cells." (PMID 38392302, 2024). "On the one hand, a dataset consisting of 1001 cancer cell lines and 481 small molecules from the CTRP database was utilized to explore the association between the expression of TMED1 and the IC50 values of diverse chemical compounds." (PMID 38392302, 2024). "TMED1 is highly expressed in multiple tumor tissues, but its prognostic significance in malignant tumors has yet to be clarified, especially in CRC." (PMID 38392302, 2024). "On the other hand, the data from the GDSC database involved 860 cancer cell lines with 265 compounds that were used to investigate the relationship between TMED1 and the IC50 of these chemical compounds." (PMID 38392302, 2024). "Few studies have reported the immune regulation function of TMED1, especially in malignant tumors." (PMID 38392302, 2024). "However, the biological behavior of TMED1 in malignant tumors has yet to be fully elucidated, especially in CRC." (PMID 38392302, 2024). "This research revealed that TMED1 is a novel prognostic biomarker in CRC and provided a valuable strategy for analyzing potential therapeutic targets of malignant tumors." (PMID 38392302, 2024). "TMED1 belongs to the TMED protein family and is overexpressed in various cancers." (PMID 38392302, 2024). "The result found that the elevation of TMED1 was positively correlated with IC50 and implied it could increase the drug resistance of cancer cells." (PMID 38392302, 2024).
tumor (1 paper, 2024). "In this study, the expression of TMED1 and the association with the tumor’s primary location, as well as the T stage, were analyzed." (PMID 38392302, 2024). "In this study, it was found that TMED1 expression substantially increased in CRC tumor tissues compared to normal tissues in the TCGA, GEO, and CPTAC datasets." (PMID 38392302, 2024). "A Sankey diagram was used to visualize the primary tumor sites, T histopathologic stage, TMED1 expression, and survival status in CRC patients." (PMID 38392302, 2024). "Based on these findings, TMED1 may be a novel tumor oncogene and prognostic biomarker for CRC." (PMID 38392302, 2024). "It indicated that the protein level of TMED1 was elevated in tumor samples as opposed to samples from normal tissues (p < 0.01)." (PMID 38392302, 2024).
TMED1 also shares sentences with these, for which no sentence is quoted: adenocarcinoma (1 paper); colon adenocarcinoma (1); rectum adenocarcinoma (1).